C9 (complement C9)
Diseases named in the same sentence as C9 in open-access papers (continued):
Sharing a sentence is not in itself a finding about the gene and the disease.
tumor (37 papers, 1998 to 2025). "As hypoxia is a main hallmark of tumor microenvironment, we treated the MIMs in low-oxygen environment for 12 h and tested the expression of C9." (PMID 29900010, 2018). "Results showed that high expression of C9 in TAMs positively associated with tumor necrosis (P = 0.024) and was negatively correlated with lymph node metastasis (P = 0.025), suggesting that C9 played a crucial role in NSCLC development." (PMID 29900010, 2018). "However, in tumor microenvironment, hypoxia switched the immunophenotype of macrophages from M1 to M2 forms, which accompanying with the downregulation of C9 in TAMs, and leading to loss of tumoricidal activity." (PMID 29900010, 2018). "Furthermore, immunofluorescent staining revealed that C9 specifically expressed in most alveolar macrophages (AMs) in adjacent lung tissues and a small fraction of tumor-associated macrophages (TAMs) in NSCLC tissues." (PMID 29900010, 2018). "Another study looking at blood biomarkers with an impact on GBM biology found that leucine-rich alpha-2-glycoprotein (LRG1), C-reactive protein (CRP), and complement component C9 (C9) were correlated with tumor size." (PMID 39057054, 2024). "The downstream activation of terminal complement components results in the assembly of the pore-forming membrane attack complex (MAC or C5b–C9) on the tumor cell membrane, which promotes the terminal lytic pathway." (PMID 39125956, 2024). "Consistently, the expressions of C7 and C9 in tumor tissues were confirmed to be downregulated in tissue microarray (TMA) compared with adjacent normal tissues." (PMID 35929594, 2022). "Immune and stromal cell populations included 2 populations: Macrophages 1 (c1: C1qa, C1qb, C3aR1, Cd68, Csf1r, Tlr2, and Cd86) and 2 (c6 + c9: Ccr7, Csf2rb, Il1b, and Cd74) expanded in PNs as a percentage of total tumor cells." (PMID 36134665, 2022). "The blood biomarkers (LRG1 (Leucine Rich Alpha‐2‐Glycoprotein 1), CRP (C‐Reactive Protein) and C9 (Complement C9)) revealed significant positive correlations with tumour size." (PMID 32696617, 2020). "In fact, the hypoxic tumor microenvironment can shift the phenotype of macrophages from M1 to M2 and down-regulate the expression of C9 in TAMs, which means that improving the hypoxic environment of tumors is an important strategy for tumor treatment." (PMID 33224886, 2020). "Conversely, C9 Pdcd10-ko cells showed up-regulation of a large set of tumor tip cell markers, which were less modified in C1 and C6." (PMID 33138917, 2020). "C9 is specifically expressed in most alveolar macrophages (AMs) in adjacent lung tissues, but only a few tumor TAMs in NSCLC tissues." (PMID 33224886, 2020). "Both western blot assay and IF staining indicated that the protein level of C9 was significantly decreased after 12 h hypoxia treatment, compared with normoxia culture, which accounted for the down expression of C9 in TAMs in tumor microenvironment." (PMID 29900010, 2018). "In other words, local C9 is an important supplement for CDC-mediated immune surveillance in tumor microenvironment." (PMID 29900010, 2018). "The plasma concentrations of LRG1, CRP, and C9 showed significant positive correlations with tumor size (R2 = 0.534, 0.495, and 0.452, respectively)." (PMID 29513714, 2018). "Importantly, the concentrations of C9, CRP, and LRG1 are significantly associated with tumor size, reinforcing their potential role in GBM prognosis and clinical stratification." (PMID 40628732, 2025). "As a complement component that is linked to inflammation and immune response, C9 is unlikely to provide specific information predicting tumor formation." (PMID 38383428, 2024). "To this end, we examined the deposition of C1q, C3 and C9 in the tumor masses using IF." (PMID 38017492, 2023).
tumor (continued). "Moreover, GP1 displayed increased expression of angiogenic features (e.g., ANGPTL4, EGFR, AAMP) and complement and coagulation cascade components (e.g., C1, C7, C8, C9, PLG, SERPINE1), which have been associated with aggravated tumor invasion." (PMID 35440542, 2022). "Although heterogeneous relative to tumor type, complement proteins expressed by malignant cells are variable; in general, tumor cells express low C8 and C9 but highly express C3 and the regulators factor H, factor I and especially the membrane regulators CD46, CD55 and CD59." (PMID 33147799, 2020). "Previous studies had shown that CD59 was highly expressed in a variety of solid tumors and cells, acting as a complement regulatory protein that prevented MAC formation by binding to C8 or C9, thereby protecting tumor cells from complement-mediated cytolysis and evading immune detection." (PMID 30636930, 2019). "In addition, nontumor tissues with tumoricidal activity contained more C9-positive cells than others without effect (P < 0.01), which further supporting our in vitro finding that C9 plays crucial role in tumor cell lysis." (PMID 29900010, 2018). "Results showed that high expression of C9 in TAMs associated with necrosis inside of cancer tissues, suggesting that CDC might lead to a large number of tumor cells lysis." (PMID 29900010, 2018). "Therefore, a conclusion is drawn that resident macrophage-derived C9 can inhibit tumor progression combining with systemic complement components." (PMID 29900010, 2018). "Finally, we unveiled that hypoxic tumor microenvironment could switch the phenotype of macrophages from M1 to M2 forms, accompanying with the downregulation of C9 in TAMs." (PMID 29900010, 2018). "It is well known that both AMs and TAMs are differentiated from PBMs27,28, but the expressions of C9 between them are significantly different despite the high expression of C9 in PBMs, which indicates that the specific tumor microenvironment may regulate the expression of C9 in TAMs." (PMID 29900010, 2018). "Among the most promising biomarkers, the overexpression of complement component C9 (C9), C-reactive protein, and leucine-rich α-2-glycoprotein (LRG1) is strongly correlated with GBM tumor burden and progression." (PMID 40628732, 2025). "The methods used here focus on the terminal complement component in MAC formation due to the raised circulating C9 previously identified, and the specific outcomes of MAC formation in cancer affecting tumor growth, cell death, and migration." (PMID 35345676, 2022). "C9 is part of the membrane attack complex (MAC) and has been shown to modulate cellular behavior in the tumor microenvironment (TME)." (PMID 35982973, 2022). "Among them, leucine-rich alpha-2-glycoprotein (LRG1), complement component C9 (C9), and C-reactive protein (CRP) showed significant positive correlations with tumor size." (PMID 35806478, 2022). "Pearson correlation analysis showed a significant positive correlation between plasma protein concentrations and tumor size for CRP, C9, and LRG1." (PMID 29513714, 2018). "In such neoplastic disease models, the added effect of host immune responses in the form of selectively “targeted” antibody-dependent cell cytotoxicity (ADCC), complement C9 mediated cytolysis, and/or opsonization/phagocytosis would have been realized." (PMID 25821636, 2015). "The supportive role of the tumor micro-environment is represented by proteins involved in avoiding immune destruction and inducing tumor-promoting inflammation (CRP, C9, SERPINA3)." (PMID 25114662, 2014). "In the present study, C1q, C3 and C9 were detected by IF only in the tumor mass of animals treated with AT101 and not with non-specific IgM, that have no specificity for tumor cells." (PMID 38017492, 2023). "But in tumor, a lot of TAMs were CD163 and HIF1α-positive, and less expressed HLA-DR and C9." (PMID 29900010, 2018).
tumor (continued). "But the expression of C9 in TAMs is not related to the tumor size, which may be because that some tumor cells can escape the complement attack via many mechanisms." (PMID 29900010, 2018). "Therefore, it seems logical that C9 as a biomarker could be used to monitor carcinogenesis and cancer progression, but its precise role in tumor microenvironment is not clear." (PMID 29900010, 2018).
infection (34 papers, 2010 to 2025). The state of being infected such as from the introduction of a foreign agent such as serum, vaccine, antigenic substance or organism. "The amount of C9 tissue staining was evaluated in septic versus aseptic tissue and the amount of C9 staining was correlated with the different pathogens causing the infection." (PMID 36895567, 2023). "A deficiency in C9 results in an inability to assemble the membrane attack complex, with a subsequent increase in susceptibility to infection." (PMID 36638126, 2023). "To examine if C9 deficiency has any effect on R. australis pathogenesis, we examined the concentration of bacteria in the infected liver over the time course of the infection." (PMID 29581196, 2018). "Combining the biological functions of the C9 protein and these previous studies, our result that an increase in the abundance of C9 protein (lower susceptibility to infection) in the plasma of young, healthy pigs is genetically associated with better feed efficiency under challenge is plausible." (PMID 36638126, 2023). "Overall, infection with Neisseria meningitidis appears to be the most common infectious complication of complement deficiency, and this is by far the most common infection in those with deficiencies in terminal complement proteins (i.e. C5 – C9)." (PMID 22551888, 2012). "Complement is a humoral factor of innate immunity and plays a crucial role in the fish immune response to pathogen infection, including C1q, C3, C5b, C6, C7, C8, C9, etc.." (PMID 41154820, 2025). "C9 forms part of the membrane attack complex (or C5b-9) that is used to lyse targeted cells, and C9 also contributes to inflammasome activation during infection." (PMID 39014464, 2024). "Further experiments will be needed to validate the possible use of C9 immunostaining for a more reliably detection of CN-PJIs and low-grade infections." (PMID 36895567, 2023). "The response to the Alpha shows that both complement C4 and C9 increase greatly in the pre-infection group after first vaccination (9.6-fold and 93-fold, respectively)." (PMID 35975199, 2022). "This indicates pre-infection elicits greater C4 and C9 against VoC binding after a second antigen exposure." (PMID 35975199, 2022). "C5 and C9 participate in the complement activation pathway, and the complement system is a main line of defense against infection." (PMID 32365127, 2020). "When apaf-1−/− MEFs were treated with Ap-i, the incremental increase in the C. pneumoniae infection rate was negated; however, C9-i still decreased the infection rate." (PMID 26290316, 2015). "Such response was observed in our experimental model since it was observed presence of binding of antibodies, C3 and C9 components to trophozoites during all time points of infection." (PMID 20338063, 2010). "Understanding how Pet prevents C9 polymerization is important in the context of an infection and may represent one of the strategies employed by E. coli to evade the complement system in the bloodstream." (PMID 38371299, 2024). "Due to the unclear sampling area, some samples could be closer to the infection site than other samples, explaining the variety in the percentage of C9 immunostaining in the tissue samples." (PMID 36895567, 2023). "Complement C9 abundance rose in both cohorts during infection, and reached a similar maximum." (PMID 30774579, 2019). "Although C9 deficiency is not lethal, it is associated with increased risk of chronic, recurring infection with Neisseria meningitides and Neisseria gonorrhea." (PMID 27857713, 2016). "In comparing the groups with and without infection, the SNPs most significantly associated with infection were located in complement genes, including C3, C5, C6, C7, C9 and MBL2 (P < 10−6)." (PMID 27063552, 2016). "Post infection, cells were incubated with and without C9 and luminescence readings were compared at time points from 17 to 20 h." (PMID 36309730, 2022).
infection (continued). "In addition, the expression of c1ql2, C3, C5, C7, C9, CFB, and complement factor H (CFH) was regulated in rainbow trout stimulated with β-glucan upon infection with A. salmonicida, suggesting improved immune enhancement." (PMID 34835165, 2021). "In addition, we classified the patients into subgroups based on the infection with DENV-1 or DENV-2 and compared the levels of C2, C4b, C5, C5a, C9, factor D and factor I between these classified groups." (PMID 32913345, 2020). "Therefore, we think that the phase of infection is not the reason for some septic samples being negative for C9 immunostaining." (PMID 36895567, 2023). "A reason might be that the complement pathway is mainly activated in the early phase of infection and that C9 is not present in later stages of infection." (PMID 36895567, 2023). "The complement factors C3, C9, and CFHR3 (complement factor H-related protein 3 precursors) were down-regulated with the wt isolate, which could be related to an attempt of the virus to regulate the inflammatory response during infection." (PMID 35215144, 2022). "Furthermore, we did not analyze specifically if low-grade infections could be identified more clearly with the help of C9 staining, to help identify PJI in unclear cases." (PMID 36895567, 2023). "Furthermore, a broad activation pattern of the complement system—encompassing both effector components (e.g., C2, C3, C8A, C9) and regulatory proteins (e.g., CFH, CFI, C1QB)—is consistent with prolonged innate immune stimulation in the absence of active infection." (PMID 40869330, 2025).
cancer (30 papers, 2007 to 2025). A tumor composed of atypical neoplastic, often pleomorphic cells that invade other tissues. "Although an association with cancer of each cognate protein has already been reported, and furthermore, C9 glycoforms have been suggested to have biomarker value, epitopes with characteristic association patterns have not been described." (PMID 37211046, 2023). "Since the iTAAs and complement (C) are associated with cancer therapy Immunofluorescence (IF) was applied to evaluate the expression of the iTAAs and C3, C5, C9." (PMID 37336938, 2023). "As a consequence, we found cancer stem cell-associated proteins, such as mmp2, mmp9, mmp13, mmp14, paxillin, Ras, src and c-myc, as well as genes expressed in the immune system, such as C5, C9, and HMGB1." (PMID 31832023, 2019). "Low expression of terminal elements (C8A, C8B, and C9) was detected in all cancer types, whereas complement regulators (C1inh, FH, FI CD46, CD55, and CD59) are highly expressed in most cancers." (PMID 38003705, 2023). "We observed that individual LC-associated proteins, such as complement component 9 (C9), C4b-binding protein (C4BP), α2-HS-glycoprotein, and CFH, display both cancer-associated and neutral epitopes." (PMID 37211046, 2023). "Another possibility is that cancer cells produce C9, and this C9 is “different” from C9 produced by the liver." (PMID 37762663, 2023). "Attachment of complement-activating proteins such as CVF, C3b, C7, or C9 directly to therapeutic antibodies represents an alternative means to strengthen complement attack and thereby to overcome complement resistance of cancer cells." (PMID 31024572, 2019). "As anticipated, AGI-134 induced the deposition of complement C3b/C3bi and led to the formation of the membrane attack complex (MAC) C5b-C9 on A549 cancer cells." (PMID 31889898, 2019). "In all, 35/104 of cancer tissues showed relative higher expression of C9 in TAMs (C9+/CD68+ ≥10%) compared with the others (C9+/CD68+ <10%)." (PMID 29900010, 2018). "Our search in the Proteome Atlas indicates C9 protein and mRNA expression in some cancer cells." (PMID 37762663, 2023). "Based on these findings, we postulated that the differential localization of C9 and C5b-9 could be explained if C9 is being expressed in the epithelial/cancer cells, while the C5b-9 is being deposited as MAC." (PMID 35345676, 2022). "While additional EAC cohort evaluation for total serum C9 remains to be conducted, the multiple independent reports of elevated serum C9 or glycoforms of C9 in multiple cancers support the mounting evidence for complement system dysregulation in cancer." (PMID 34201241, 2021). "These include: CDH1, MUC1, THBS4, and MSLN for PEs related to cancer; ADA2, CXCL10, and WARS for TB-PEs; CRP, S100A9, and VIM for parapneumonic PEs; and C9, LDHA, HPX, LDHB, and C3 for benign-PEs." (PMID 35197508, 2022). "CD59 has several additional functions relevant to immune function, including the complement activation cascade where it binds to C8 and C9 to inhibit the formation of membrane attack complex (MAC) pores, conferring cancer cells resistant to complement-mediated cell lysis." (PMID 39436703, 2024). "Immunohistochemical labeling for C3d (polyclonal) and C9 neoantigen in nontumorous parts of cancer nephrectomy kidney tissue showed tubular staining in cortical tissue." (PMID 34927448, 2022). "In line with activation of the complement cascade, elevated plasma/serum C9 was reported for gastric and colorectal cancer, although terminal complement activity and formation of C5b-9 in the cancer tissue was not examined." (PMID 35345676, 2022).
cancer (continued). "Future evaluation and comparison of the C9 changes in different cancers will be required to determine if JAC-C9 and the final biomarker panel for EndoScreen Chip are EAC-specific or overlap with another cancer type." (PMID 34201241, 2021). "C9 and SERPINA3 are elevated in blood of patients with various types of cancers." (PMID 29513714, 2018). "Should the complement cascade override the effects of CD55 (and CD46, another mCRP) and manage to activate the terminal complement components on cancer cell membranes, functional CD59 molecules bind to human C8 and C9, during the attempt to properly assemble the membrane attack complex." (PMID 17623109, 2007). "Immune suppression may involve the immune checkpoint pathway, whereby c5, c8, and c9 subtypes tend to show high expression of ligands such as PDL1 and PDL2 (presumably expressed by cancer cells), as well as high expression of the corresponding receptors associated with T cells." (PMID 28775315, 2017). "Moreover, some human cancer cells, such as U938, HL60, and B-CLL cells, could be lysed by C5b-8 alone, in the absence of C9, when a sufficient number of complexes were deposited on them." (PMID 31024572, 2019).
bacterial infection (4 papers, 2018 to 2022). "The C9 deficiency in neonatal serum has been associated with poor defences against bacterial pathogens 33, with premature infants having particularly low C9 levels at even higher risk of bacterial infection." (PMID 32714087, 2020).
immune disorders (3 papers, 2015 to 2023). "C9 is a domain protein that is closely related to immune system diseases." (PMID 36178657, 2023). "Our previous study identified a tetradecapeptide derived from Trichinella spiralis paramyosin (Ts-pmy) that could bind to human complement component C9 to inhibit its polymerization, making the peptide a candidate therapeutic agent for complement-related immune disorders." (PMID 33424810, 2020).
cardiovascular disease (1 paper, 2025). "We found 6 proteins that mediated the PGSCAD’s effect on MACE in EXSCEL (C9, LBP, ITIH4, APOM, CES1, and HS6ST2), providing supporting evidence that they might serve as biomarkers for cardiovascular disease in patients with T2D52–54." (PMID 40032831, 2025).